AKT1 (AKT serine/threonine kinase 1)
Diseases named in the same sentence as AKT1 in open-access papers (continued):
Sharing a sentence is not in itself a finding about the gene and the disease.
cancer (continued). "This study can potentially aid in developing effective and selective AKT1 inhibitors to control cancer." (PMID 36985568, 2023). "As such, AKT1 is involved in multiple pathways including cell cycle progression and cell survival, and is hyperphosphorylated, which activates AKT1 in over 50% of human cancers." (PMID 36937454, 2023). "AKT1 is activated and hyperphosphorylated in most human cancers by at two key regulatory sites (Thr308 and Ser473)." (PMID 38264327, 2023). "AKT1 dysregulation leads to tumorigenesis processes, including cancer cell proliferation, growth and survival, tumor angiogenesis, recruitment of inflammatory cells required for the tumor microenvironment and resistance to apoptosis." (PMID 37895906, 2023). "The dearth of knowledge regarding AKT3 in cancer possibly stems from early reports that it is expressed predominantly in the brain, heart and kidneys, whereas AKT1 and AKT2 are expressed ubiquitously." (PMID 37292818, 2023). "Most genes were significantly correlated with gastric inflammation-cancer transformation, such as AKT1, EGFR, and MYC." (PMID 37964307, 2023). "Currently reported underlying mechanisms of LAMC2-induced cancer cell progression and metastasis include regulation of integrin B1-, ZEB1, and Snail expression, as well as activation of AKT1 and EGFR." (PMID 37542131, 2023). "Phospho-ERK1/2 and phospho-Akt1/2/3 are known downstream effectors of KRAS in the MAPK signaling in cancer cell lines." (PMID 37051535, 2023). "The AKT1 enzyme has been found to be overexpressed in various malignancies and, hence, is considered a prospective target for the development of anti-cancer therapeutics." (PMID 36985568, 2023). "It is evident from the UALCAN database (TCGA) that expression of AKT1 is higher in cancer as compared to normal samples." (PMID 36985568, 2023). "The present computational study is a prediction for evaluating the specific interactions between the chosen natural ligands and AKT1, an overexpressed protein in cancer." (PMID 36985568, 2023). "The compound, MK-2206, an inhibitor of the protein kinases AKT1/2/3, is undergoing evaluation in multiple clinical trials for the treatment of certain types of cancers, including those resistant to erlotinib." (PMID 37521473, 2023). "It is phosphorylated by Akt1 on residue S39, stabilised, and thereby regulates cancer cell invasion in aggressive sarcoma." (PMID 38002001, 2023). "Due to their significant role in numerous cellular mechanisms closely associated with cancers, HSPGs, such as SDC4, and HSPG-related genes such as AKT1 and ATM present an exciting target for BC diagnostics and macromolecular drug therapies." (PMID 36152082, 2023). "Many studies report 14-3-3ζ works as a central point to promote oncogenic and chemoresistance pathways in cancers such as PI3K/Akt1, Erk/Mapk and TGF-β." (PMID 36776326, 2023). "293T treated with BLM and with an inhibitor of AKT1 (AZD5363) to mimic cancer treatments that suppress AKT1 activity." (PMID 37343701, 2023). "We computationally investigated a few phytochemical flavonoids to establish their mechanism of action and potential to inhibit AKT1, a therapeutic cancer biomarker." (PMID 36985568, 2023). "The results of our study provide a new strategy for using PARPi alone or in combination with DNA-damaging agents (radio or chemotherapy) to treat ARID1A-mutated cancers, as well as many other PI3K/Akt1-induced cancers." (PMID 36910637, 2023). "The EGFR protein was pivotal in inducing tumor promotion and in impeding apoptosis in cancer cells by inducing phosphorylated AKT serine/threonine kinase 1 (pAKT) and nuclear factor kappa B (NFκB)." (PMID 38139811, 2023).
cancer (continued). "Each Akt isoform has been demonstrated to play different and specific roles in cancer cells signaling; indeed, Akt1 and Akt2 displayed opposite roles in cell cycle progression, migration and invasion among different types of human cancers." (PMID 36769122, 2023). "In 2022, three computer-aided drug discovery (CADD) approaches described the identification of new competitive AKT1 small molecule inhibitors endowed with anti-cancer activities." (PMID 37513905, 2023). "It was also established through Cytoscape STRING analyses that AKT1 is not only the focal point of the target interaction network but also interacts with established druggable targets against different types of cancers." (PMID 37766164, 2023). "The hyper-phosphorylation of AKT1 was found in over 50% of human tumors thus inhibition of AKT1 kinase activities is the potential therapeutic target for cancer treatment." (PMID 37627018, 2023). "A randomized controlled trial found that AKT1 is an important core target for the treatment of cancer-induced fatigue." (PMID 37101547, 2023). "We showed that PI3K/Akt1 pathway plays an important role in the sensitization of cancer cell lines with compromised function of ARID1A to PARPi treatment." (PMID 36910637, 2023). "Alternatively, several synthesized and natural compounds have shown cancer chemoprevention potential against cancer targets, including AKT1." (PMID 36985568, 2023). "Aside from the AKT1’s well-documented role in promoting cancer survival, emerging evidence implicates AKT1 in reducing the expression and impeding the nuclear accumulation of β-catenin, consequently reducing invasive potential." (PMID 37345165, 2023). "Docking analyses reveal that tehranolide has the most efficiency in inhibiting AKT1 and has the potential to be used for the therapeutic management of cancer." (PMID 36985568, 2023). "An important aspect of the development of cancer is cell migration and motility, in different malignancies, Akt1 activation and expression leads to the advancement of carcinogenesis and metastasis." (PMID 37347115, 2023). "This study reports four natural phytocompounds with strong binding affinities and inhibitory effects against AKT1, indicating their potential as anti-cancer therapeutics." (PMID 36985568, 2023). "Akt1 is involved in the regulation of tumor growth, tumor cell invasion, and chemoresistance, and it is the main isoform found in various cancers." (PMID 36782251, 2023). "The activation of AKT1 further stimulated downstream pathways to promote cancer cell proliferation, invasion, and metastasis angiogenesis." (PMID 36654811, 2023). "It has been shown that the inhibition of phosphorylated Akt1 (pAkt1) activates miR-145 expression in human cancer cells." (PMID 35563814, 2022). "In conclusion, positive regulation of PI3K signaling and negative regulation of PTEN signaling can induce Akt1 activation in human cancers." (PMID 36539659, 2022). "We found that ac4C peaks in the genes associated with the cancer pathway (BCL9L), the cell cycle (AKT1) and stem cell maintenance (SOX4) decreased in the NAT10 knockdown UMUC‐3 cells." (PMID 35522942, 2022). "Recent studies have reported that AKT1 plays a dual role in cell proliferation, migration and invasion depending on the type of cancer cell." (PMID 36286049, 2022). "Accordingly, we searched the literature via Google Scholar and PubMed and found novel information for networking the AKT1-, AKT2-, and AKT3-associated circRNAs and cell functions, especially for cancer cells." (PMID 36230902, 2022). "PI3K-Akt signal transduction is usually destroyed in human cancer, and AKT1 is an important part of this pathway, which affects multiple processes directly involved in tumorigenesis." (PMID 35411258, 2022).
cancer (continued). "In cancer studies, miR-520a has been associated with suppression of oncogenic signaling pathways including CDK4, SUV39H1, LIMK1, GOT-2, AKT1/mTOR, and PI3K/AKT31–37." (PMID 35149732, 2022). "Inherently, AKT1 is regarded as a proto-oncogene that is overactive in various cancers, while AKT1 activation requires phosphorylation at Thr308 and further catalytic activity requires phosphorylation at Ser473." (PMID 35013126, 2022). "Owing to its remarkable role in cancer progression, AKT1 represents itself as a potential druggable target in anticancer therapeutics." (PMID 35887580, 2022). "Downregulation of AKT1/2 by miRNAs inhibits cancer cell proliferation in vitro and tumor growth in vivo." (PMID 36158660, 2022). "Miransertib (ARQ092) reduces the phosphorylation of Akt downstream substrates glycogen synthase kinase 3α (GSK-3α) and Akt activation in cancers conferring Akt1-E17K." (PMID 36180910, 2022). "Among them, AKT1 is abnormally activated and expressed in a variety of cancers, and the use of AKT1 inhibitor Ipatasertib can effectively inhibit tumor proliferation and metastasis." (PMID 35603567, 2022). "A paradoxical effect of Akt1 suppression on metastasis has also been reported in other types of cancers but with limited molecular insights." (PMID 35406397, 2022). "AKT1 is a well-validatedtherapeutic target for cancer, beinga key component of the pI3K/AKT/mTOR signaling pathway." (PMID 36442071, 2022). "Both AKT1 and EZH2 are associated with cancer metastasis and invasion, resulting in the deterioration of tumors." (PMID 35743172, 2022). "The growth of human solid tumors depends not only on rapidly proliferating cancer cells, but also on the continuous production and stationary proliferation of AKT1." (PMID 36060002, 2022). "This pathway in cancer contained the PI3K/AKT1 pathway, which includes most predicted targets and focused on AKT1." (PMID 36591458, 2022). "In the era of precision oncology, AKT1 thus represents an attractive target for the development of targeted therapies selectively hitting cancer cells characterized by an aberrant activation of the PI3K/AKT/mTOR signaling pathway." (PMID 36365115, 2022). "In the advanced cancer, AKT1 plays a specific effect in mediating tumor cell-vascular interoperability and regulates cancer metastasis through a mechanism that differs from its function of promoting tumorigenesis." (PMID 35341150, 2022). "Three novel covalent inhibitors were identified, exhibiting moderate activity against Akt1 and various cancer cell lines, potentially paving the way for future covalent allosteric inhibitors with improved properties." (PMID 35170857, 2022). "Surprisingly, despite their close sequence similarity, AKT1/2/3 have been shown to assume different roles, especially in cancer development." (PMID 35269443, 2022). "AKT1, like the other oncogene genes, plays a role in some cancers: however, here it plays significant role in the three studied cancers relative to the other oncogene genes." (PMID 35611247, 2022). "The Cancer Proteome Atlas (TCPA) created a Kaplan Meier (KM) plot for miR-520c-3p targets AKT1, AKT2, AKT3, MTOR, NF-κB (RelA), PDK1, PI3K, and PTEN." (PMID 35634241, 2022). "AKT1 is also a potential target for cancer therapy because AKT1 activation is frequently a determinant for tumorigenesis, especially in advanced cancer." (PMID 36404910, 2022). "For example, AKT1 is abnormally expressed in many types of cancer and the up-regulation of AKT1 has been known to be related to lymph node metastasis." (PMID 35430805, 2022). "In cancer, elevated Akt1 signaling is thought to be responsible for intensified glycolysis and the increase in the mevalonate pathway that causes high intracellular cholesterol production." (PMID 36139434, 2022). "Molecules such as Akt1 and TGFβ have been demonstrated to play reciprocal roles in the early and advanced stages of cancers, and epithelial-to-mesenchymal transition has been identified as a common link in the process." (PMID 35406397, 2022).
cancer (continued). "Last but not least, they have promising anticancer activity by inhibiting the pathways under investigation,VEGFR-2 and AKT-1, that end in cancer cell proliferation, growth, and survival inhibition." (PMID 35745619, 2022). "ESR1 deems to share CTNNB1-54 and AKT1-55 mediated signalling pathways to accelerate cancer and neurodegeneration, respectively." (PMID 36229517, 2022). "Based on the previous findings, AKT1 together with the other oncogene genes that are highlighted in gastrointestinal cancers, is a suitable biomarker for the mentioned cancers." (PMID 35611247, 2022). "As let-7a is a known regulator of many oncogenes, including Myc, Ras, HMGA, JAK, STAT3, and NIRF, our discovery that let-7 miRNAs regulate AKT1 phosphorylation makes them exciting new targets for the development of chemotherapeutics in AKT1-derived cancers." (PMID 35269443, 2022). "Rac1 interacts with Akt1 to increase cancer cell stemness downstream of PODXL2 and also enhance cell migration through the Axl/Rac1/Akt1-mediated axis." (PMID 35456223, 2022). "Based on that AKT1, MAPK3 and ESR1 were included in cancer pathways, as well as AKT1 and MAPK3 included in the PI3K-Akt signaling pathway, the docking results again confirmed the prediction of network pharmacology." (PMID 36034875, 2022). "To further validate the noticed modulation of AKT1 status-dependent transcriptome in patient-derived biomaterial, we attempted to search for datasets from human cancer or other studies." (PMID 35892586, 2022). "Splice variants related to four genes (DBNDD2, DAP, ITPK1, and ROGDI) previously reported upregulated in breast/other human cancers were found downregulated in AKT1 silenced samples compared to control (siNoN)." (PMID 35892586, 2022). "In the present study, we discovered that miR-145 expression levels were significantly lower in some cancer cell lines that have activated Akt1 and that activated Akt1 is positively correlated with DNA-PKcs expression." (PMID 35563814, 2022). "Other activating factors of PAM pathway, including PIK3CA mutation, AKT1 mutation, AKT2 amplification, and loss of cancer suppressor gene PTEN, can also cause resistance to anti‐HER2 agents, such as trastuzumab and lapatinib." (PMID 38089455, 2022). "PPI analysis showed potential interactions between three cancer driver genes (AKT1, KRAS, and PIK3CA) and candidate genes (CCNE2, RAD51, and NEIL3)." (PMID 36233194, 2022). "AKT1, which co-appears with "Cancer" for 1863 times and "Breast" for 477 times, ranked 10th in DriverRWH while it ranked merely 1226th in Gravity and 2233th in OncodriveFML." (PMID 35831792, 2022). "Enhanced AKT1 expression in cancer cells leads to cell proliferation and cell cycle through various downstream effectors, including cyclin D1, GSK-3, mTOR, etc.." (PMID 35646655, 2022). "By regulating EMT-related factors (like MMP2, MMP9 and fibronectin) and cell cycle suppressor (p21 and p27), Akt1/p-Akt1 involved in regulating cell motility and growth in various cancer cells." (PMID 35953860, 2022). "Although unexpected, a flurry of recent reports from various laboratories has demonstrated that Akt1 suppression in advanced cancers worsens the condition by augmenting the process of EMT, in turn promoting metastasis." (PMID 35406397, 2022). "A PPI network indicated the GNRH1 interacted with several important cancer-related proteins, including AKT1/3, MAPK1/3, and KISS1." (PMID 35646056, 2022). "Further analysis using bioinformatics prediction was performed to show that ERBB2, SRC, TNF receptor, and AKT1 are potential key targets and play an essential role in cancer treatment." (PMID 36500678, 2022). "The overexpression of AKT1, which stimulates cancer cell growth and proliferation, was found in 10–20% of the patients with PDAC." (PMID 36077529, 2022). "Aberrant/constitutive Akt1 activation is one of the etiological sources of radioresistance in cancer cells and tumors, where enhanced c-NHEJ activity appears to play a key role." (PMID 35563814, 2022).
cancer (continued). "According to bioinformatics prediction, ERBB2, SRC, TNF receptor, and AKT1 were predicted to be the key targets and play an essential role in cancer treatment." (PMID 36500678, 2022). "In HCC, lncRNA FEZF1-AS1 can compete to bind miR-4443, thereby up-regulating AKT serine/threonine kinase 1 (AKT1) expression, and ultimately promoting cancer cell metastasis and tumorigenesis." (PMID 36250718, 2022). "Previous study demonstrated that HK2 participated in regulating Akt1 and p-Akt1 expression in various cancer." (PMID 35953860, 2022). "Once activated, the AKT1 pathway reprograms cellular metabolism, thereby inducing cell growth, proliferation and survival in cancer cells." (PMID 36566195, 2022). "Pathway analysis showed that AKT1 is enriched in PI3K-AKT, MAPK and several other pathways closely related to cancer, which indicates that the gene encoding AKT1 has an important biological function in the development of cancer." (PMID 33987081, 2021). "Even though KA39 inhibited Akt1 phosphorylation to a similar extent, the greatest reduction in Akt1 phospho-form (%) was observed upon treatment at TGI concentration (μΜ) for 24 h in all three cancer cell lines." (PMID 33916378, 2021). "Aberrant expression and genetic variation of the AKT1 gene are suggested to be involved in several types of human cancers, including oral squamous cell carcinoma (OSCC)." (PMID 34150619, 2021). "Nevertheless, according to the ratio phosphoAkt1/total Akt1, Akt1 phosphorylation was significantly inhibited upon cell treatment at TGI concentration (μΜ) for 3 h in all three cancer cell lines." (PMID 33916378, 2021). "Cachectic gastrocnemius exhibited a more than 5-fold increase in the ratio of p-AMPK (Tyr112)/AMPK and significant decreases in the ratio of p-Akt1/Akt1, indicating the promoted catabolism and inhibited anabolism in cancer cachexia." (PMID 34229732, 2021). "AZD5363, a pan-AKT inhibitor, was reported to improve progression-free survival in advanced cancers with AKT1 mutations However, the number of patients with MAC is too small to draw a conclusion on the pattern of AKT1, PIK3CA, TGFβ mutation." (PMID 33738258, 2021). "Recently, with the development of next generation sequencing (NGS), cancer genomic profiling including AKT1 are now being evaluated using NGS tests." (PMID 34670536, 2021). "Calcineurin‐like phosphoesterase domain‐containing protein 1 (CPPED1) dephosphorylates AKT1 at Ser473, thereby preventing cancer progression in bladder cancer." (PMID 34009729, 2021). "Novel studies using powerful and refined methods of analysis have also shown that PI3K, along with Akt1 and the mTOR (mechanistic target of rapamycin) signaling pathway, is significantly more involved in cancer development than any other genes." (PMID 33338300, 2021). "For example, MENC recognized AKT1 (0.53% of cases) as a serine/threonine protein kinase, and its downstream proteins have been reported to be frequently activated in human cancers." (PMID 34560840, 2021). "The mRNA expression profiles of PTEN, PIK3A, and AKT1 are from the Cancer Cell Line Encyclopedia (CCLE) of the Broad Institute." (PMID 33967754, 2021). "This TIS21-mediated decrease in cancer cell motility involves AKT1-dependent downregulation of diaphanous-related formin and decreased NOX4-mediated ROS formation." (PMID 33498407, 2021). "In PCa, lower expressed miRNA-373-3p leads to the progression of cancer cells by affecting AKT1 (AKT serine/threonine kinase 1)." (PMID 34575133, 2021).